NCAM1 (neural cell adhesion molecule 1)
Diseases named in the same sentence as NCAM1 in open-access papers (continued):
Sharing a sentence is not in itself a finding about the gene and the disease.
autoimmune disease (20 papers, 2013 to 2025). A disorder resulting from loss of function or tissue destruction of an organ or multiple organs, arising from humoral or cellular immune responses of the individual to their own tissue constituents. "A subset of potential antigens, including exostosin 1 (EXT1) and EXT2, as well as neural cell adhesion molecule 1 (NCAM1), has been identified as candidates in secondary membranous nephropathy associated with autoimmune diseases, including MLN." (PMID 41440943, 2025). "MN podocyte antigens exostosin 1/eoxstosin 2 (EXT1/EXT2), neural cell adhesion molecule 1 (NCAM1), and transforming growth factor-β receptor 3 (TGFBR3) are associated with other autoimmune diseases, especially systematic lupus erythematosus (SLE)." (PMID 36405681, 2022). "The well-known NK marker CD56(NCAM-1) was upregulated in the NK cells of RA patients, supporting previous findings showing the expansion of CD56bright NK cells in various autoimmune diseases." (PMID 32365786, 2020).
colon carcinoma (19 papers, 2006 to 2024). "However, CD44, NCAM1,SYP, and NCAPG showed higher expression levels than NCM-460 in the majority of colon cancer cell lines." (PMID 35155186, 2021).
colorectal cancer (18 papers, 2003 to 2025). A primary or metastatic malignant neoplasm that affects the colon or rectum. "NCAM1, also termed CD56(+), was found to be increased in colorectal cancer patients after preoperative nutritional support, which might indicate a positive effect on the prognosis." (PMID 34613665, 2021).
Ewing sarcoma (18 papers, 2012 to 2025). A small round cell tumor that lacks morphologic, immunohistochemical, and electron microscopic evidence of neuroectodermal differentiation. "NCAM1, also known as cell adhesion molecular CD56, plays an important role in immune surveillance for the expansion of T cells, andNCAM1 over-expression in Ewing sarcoma indicates poor prognosis." (PMID 27270314, 2016).
Alzheimer disease (16 papers, 2012 to 2025). A progressive, neurodegenerative disease characterized by loss of function and death of nerve cells in several areas of the brain leading to loss of cognitive function such as memory and language. "NCAM1 and L1CAM have been implicated in cell adhesion, neurite outgrowth, and synaptic plasticity, which are processes that are disrupted in Alzheimer's disease." (PMID 38502590, 2024). "Elevated NCAM1 serum levels have been previously associated with various forms of inflammatory neuropathies and with CMT1A as well as with Alzheimer’s disease, indicating that it may be a relatively broad marker of CNS and PNS neurodegeneration." (PMID 33692503, 2021).
gastric cancer (16 papers, 2013 to 2025). A primary or metastatic malignant neoplasm involving the stomach. "Interestingly, all 3 CACNAs were predicted to interact closely with NCAM1, which has been positively associated with gastric cancer progression." (PMID 28846697, 2017). "Moreover, our current study also showed that expression of NCAM1 protein was negatively associated with gastric cancer invasion." (PMID 25860484, 2015). "In addition, the expression of COL1A1 and NCAM1 was confirmed in gastric cancer tissues and were associated with gastric cancer invasion; however, it remains unknown which miRNA(s) regulate their expression in gastric cancer." (PMID 25860484, 2015). "Further studies are required to confirm the expression status of COL1A1 and NCAM1 proteins as potential biomarkers for early diagnosis and prediction of gastric cancer progression." (PMID 25860484, 2015). "In addition, qRT- PCR and Western blot data showed an increase in COL1A1 and decrease in NCAM1 mRNA and protein levels in gastric cancer tissues." (PMID 25860484, 2015).
bipolar disorder (15 papers, 2011 to 2025). A disorder of the brain that causes unusual shifts in mood, energy, activity levels and the ability to carry out day-to-day tasks. "A T/C variant in miR-27a is associated with bipolar disorder, potentially by reducing the ability of this microRNA to target important neurodevelopmental genes like NCAM1." (PMID 35379867, 2022). "Nevertheless, in this study, we identified T/C polymorphism at rs895819 and discovered the association between miR-27a and bipolar disorder by targeting NCAM1." (PMID 35379867, 2022). "SNP rs895819, located on pre-miR-27a, is involved in the regulation of bipolar disorder by targeting neural cell adhesion molecule 1 (NCAM1)." (PMID 38203196, 2023). "To illustrate the role of rs895819 on pre-miR-27a in bipolar disorder, we combined RNA seq, luciferase reporter assay, and downstream functional experiments to identify NCAM1 as a target gene of miR-27a in NPC." (PMID 35379867, 2022). "We have exploited this technique to sequence the coding, intronic and flanking sequence of ST8SIA2 and its region of interaction in NCAM1, in lymphocyte DNA from individuals with bipolar disorder." (PMID 24651862, 2014). "This all provides evidence for our hypothesis that miR-27a is involved in the etiology of bipolar disorder by targeting NCAM1." (PMID 35379867, 2022). "All these indicate that miR-27a and its target NCAM1 may play an important role in bipolar disorder." (PMID 35379867, 2022). "To explore the role of sequence variation affecting PSA-NCAM formation, we conducted a targeted re-sequencing study of a ∼100 kb region – including the entire ST8SIA2 gene and its region of interaction with NCAM1 – in 48 Caucasian cases with bipolar disorder using the Roche 454 platform." (PMID 24651862, 2014).
cervical carcinoma (15 papers, 2002 to 2025). A carcinoma arising from either the exocervical squamous epithelium or the endocervical glandular epithelium. "As it relates to cervical cancer, NCAM1 downregulation has been shown to be associated with carcinoma in situ of the cervix in comparison to its levels in women with HPV infections in the absence of dysplasia." (PMID 36675007, 2023). "The downregulated NCAM1 observed in CIN3 biopsies in the transcriptomic study is expected, as phenotypic alterations and functional deficiencies of NK cells have been found in patients harbouring HPV16 infections and cervical cancer." (PMID 39712018, 2024). "In conclusion, NCAM1 and CDKN2A are two promising candidates to distinguish whether women are at high risk of developing cervical cancer and in need of frequent follow-up." (PMID 35008799, 2021).
malaria (14 papers, 2009 to 2026). Malaria is a serious and sometimes fatal disease caused by a parasite that commonly infects a certain type of mosquito which feeds on humans. "Circulating levels of S100B, Tau, UCH-L1, BDNF, and NCAM-1 have been documented in previous malaria studies." (PMID 39658124, 2024). "A subset of adaptive NK cells characterized by the lack of CD56 (NCAM1) and higher expression of inhibitory receptors LAG3 (CD223) and LILRB1 (CD85j) correlated with reduced parasitemia and protection against malaria symptoms in the subsequent year." (PMID 37939134, 2023).
breast tumors (13 papers, 2015 to 2024). "The breast tumour NCAM1-positive subtype that does not appear to have a counter part in the adult peripheral blood, is a strong IFNγ producer and higher expression of innate gene signature." (PMID 33268347, 2021).
diabetes (13 papers, 2008 to 2025). "GSEA found enrichment of phototransduction cascade, enrichment of complex IV activity, and decrease in NCAM1 interactions in neuronal cells in response to diabetes." (PMID 39739865, 2024).
epilepsy (13 papers, 2013 to 2025). A brain disorder characterized by episodes of abnormally increased neuronal discharge resulting in transient episodes of sensory or motor neurological dysfunction, or psychic dysfunction. "Neural cell adhesion molecule 1 (NCAM-1) serum abnormalities were demonstrated in epilepsy and linked to Parkinson’s disease and autoimmune encephalitis." (PMID 36289630, 2022). "Intensive NCAM-1 content was also detected in drug-resistant epilepsy patients when compared to the drug-effective patients." (PMID 30298130, 2018). "NCAM-1 concentration in cerebrospinal fluid was found elevated in epilepsy patients in comparison to healthy individuals." (PMID 30298130, 2018). "Therefore, NCAM-1 concentration in cerebrospinal fluid could be considered a biomarker for epilepsy." (PMID 30298130, 2018). "The ROC curves revealed that the expression levels of key genes NCAM1, CPVL, PECAM1, and TNC had high accuracy in classifying epilepsy and control groups (AUC >0.9)." (PMID 40520613, 2025). "Fifteen potential key genes in epilepsy were identified, including RPS6KA3, CTSD, and NCAM1." (PMID 40520613, 2025).
Stroke (13 papers, 2016 to 2025). Sudden impairment of blood flow to a part of the brain due to occlusion or rupture of an artery to the brain. "The neuronal markers NCAM1 and Syn1 were upregulated, but only the increase in NCAM1 reached significance (**p = 0.0079), indicating that neurons could significantly contribute to the BDEVs pool 72 h after stroke." (PMID 35639208, 2022).
Anxiety (12 papers, 2015 to 2025). Intense feelings of nervousness, tension, or panic often arise in response to interpersonal stresses. "Interestingly, the largest GWAS study identified six genetic susceptibility loci that were significantly associated with IBS, four of which were located in genes associated with mood and anxiety (NCAM1, CADM2, PHF2/FAM120A, DOCK9)." (PMID 36071849, 2022).
cholangiocarcinoma (12 papers, 2010 to 2025). A carcinoma that arises from the intrahepatic biliary tree (intrahepatic cholangiocarcinoma) or from the junction, or adjacent to the junction, of the right and left hepatic ducts (hilar cholangiocarcinoma). "Other oncogenic pathways included those known to contribute to poor prognosis in cholangiocarcinoma yet which are poorly defined in terms of their components, such as MET and NCAM1." (PMID 37095160, 2023).
metastatic disease (12 papers, 2014 to 2025). "Polysialic acid is often present on NCAM1 (neural cell adhesion molecule 1), and expression correlates with metastatic disease and poor clinical prognosis." (PMID 36077781, 2022).
Cognitive impairment (11 papers, 2011 to 2023). Abnormal cognition is characterized by deficits in thinking, reasoning, or remembering. "It is possible that when the nervous system is damaged to the extent which causing cognitive impairment, miR-572 expression will be down-regulated to promote NCAM1 expression, initiating the repair mechanisms to promote cognitive function restoration." (PMID 25680004, 2015). "Moreover, proteins associated with cognitive impairments, like GRN, ARSA, NCAM1, and GUSB, also showed marked differences in protein levels." (PMID 32850779, 2020).
NK/T cell lymphoma (11 papers, 2012 to 2023). "In human diseases, NCAM1 has been expressed in various tumors of the nervous system, malignant NK/T-cell lymphomas and neuroendocrine carcinoma." (PMID 31477684, 2019).
autism (9 papers, 2017 to 2025). Persistent deficits in social interaction and communication and interaction as well as a markedly restricted repertoire of activity and interest as well as repetitive patterns of behavior. "NCAM1 has also been implicated in neurological disorders, such as autism and possibly other neuroinflammation‐related diseases." (PMID 39924344, 2025). "For example, we have found that NCAM1 polymorphisms is associated with autism in a previously undiagnosed case in year 2014." (PMID 30687093, 2018). "NCAM1 could be suggested as a possible biomarker, capable of contributing to the diagnostic process of the autistic disorder." (PMID 34676183, 2021).
Immunodeficiency (9 papers, 2010 to 2025). Failure of the immune system to protect the body adequately from infection, due to the absence or insufficiency of some component process or substance. "Despite there being little evidence to support the involvement of NCAM in inflammatory and immune disease, there is some indication of NCAM1 mediating inflammatory cascades that underlie inflammatory disease." (PMID 35492721, 2022). "Among the four genes that were consistently upregulated in ARHL patients (FASLG, NCAM1, MARCO, and NECTIN1), FASLG was prioritized for further validation based on its strong association with immune-mediated apoptosis and its previously reported role in age-related immune dysfunction." (PMID 40971385, 2025).
asthma (8 papers, 2015 to 2025). "Rs35576001in NCAM1 was associated with asthma in European Americans including the ESP as controls (rs35576001, p = 5.0x10-5), however, the same variant was protective for persistent wheeze among African Americans with severe RSV bronchiolitis in infancy (p = 0.021)." (PMID 26587832, 2015). "We similarly observed an association with asthma following severe RSV bronchiolitis and rare nonsynonymous variants in FLG and NCAM1 in European Americans, and NOS1 in African Americans." (PMID 26587832, 2015). "Further validation of these variants through Sanger sequencing in asthma cases confirmed the presence of the minor allele in 6 carriers of rs1800888 in ADRB2 (European Americans), one carrier of rs35576001 in NCAM1 (a European American), and one carrier of rs76090928 in NOS1 (an African American)." (PMID 26587832, 2015).
type 2 diabetes (8 papers, 2009 to 2026). "Here, we have extended this approach toward type II diabetes by assessing the efficacy of the CPP construct, designated as neural cell adhesion molecule-1 (NCAM1)-prion protein (PrP), in inhibiting IAPP oligomerization, fiber formation, and associated cytotoxicity." (PMID 41926749, 2026).
ameloblastoma (7 papers, 2014 to 2025). The most common odontogenic tumor, arising from the epithelial component of the embryonic tooth and usually affecting the molar-ramus region of the mandible or maxilla. "NCAM1 was confirmed to be up-regulated mediated by miR-141-3p and inhibited ameloblastoma cell migration." (PMID 36817451, 2023). "Overexpression of Neural Cell Adhesion Molecule 1 significantly inhibited the migration of ameloblastoma cells and was regulated by miR-141-3p." (PMID 36545127, 2022).
medulloblastoma (7 papers, 2010 to 2025). A malignant, invasive embryonal neoplasm arising from the cerebellum. "Both proteins of DLL1 and NCAM1 are detected in medulloblastoma tissues of patients in four subgroups: WNT, SHH, group 3 and group 4." (PMID 34857809, 2021).
metastatic carcinoma (7 papers, 2015 to 2025). A carcinoma which has spread from the original site of growth to another anatomic site. "Results revealed a higher Mesenchymal markers in primary cancer cells (e.g., NCAM1, LAMB1, SERPINE1, TCF4, VIM, ZEB1, and ZEB2) and a higher Epithelial markers in metastatic cancer cells (e.g., CDH1, CLDN4, ELF3, EPCAM, KRT18, KRT7, and KRT8)." (PMID 37202394, 2023).
astrocytoma (6 papers, 2014 to 2025). "Other proteins overexpressed in astrocytomas have also been implicated in tumor growth and invasion, such as the inter-cellular adhesion molecule 1 (ICAM-1), the neural cell adhesion molecule NCAM1 and the thrombomodulin (THBD)." (PMID 25360666, 2014).
heart failure (6 papers, 2020 to 2024). Inability of the heart to pump blood at an adequate rate to meet tissue metabolic requirements. "Moreover, we observed that NCAM1 was radically low expressed in patients suffering heart failure." (PMID 33224271, 2020).
mood disorder (6 papers, 2011 to 2023). A cognitive disorder a disturbance in which the person's mood is hypothesized to be the main underlying feature. "Brain expression of NCAM1 and CADM2 was implicated in our colocalization analysis: both regulate neural circuit formation and influence changes in white matter microstructure found in both mood disorders and IBS25,41,42." (PMID 34741163, 2021). "As already mentioned under ENS above, the genes NCAM1 and CADM2 were two genes which regulate neural circuit formation and influence changes in white matter microstructure in IBS and mood disorders." (PMID 36732586, 2023).
adenoma (5 papers, 2008 to 2025). A neoplasm arising from the epithelium. "Focusing on the promoter methylation status of the neuroendocrine markers chromogranin A (CgA), chromogranin B (CgB) and CD56 (NCAM1) confirmed congruently lower methylation levels in NETs and PitNETs/adenomas compared to adenomas." (PMID 41060331, 2025).
bladder cancer (5 papers, 2013 to 2025). "Similarly, NCAM1 is expressed at lower levels in bladder cancer cell lines than in normal urothelial epithelial cells and its silencing enhances bladder cancer cell proliferation." (PMID 39781359, 2025). "NCAM1, a cell adhesion protein, may reduce cell invasion and potentially contribute to bladder cancer recurrence." (PMID 41153362, 2025).
coronary artery disease (5 papers, 2020 to 2025). "Previous studies showed that NCAM1 levels were lower in coronary artery disease and significantly related to a high hazard of coronary artery disease." (PMID 33224271, 2020). "Expression of NCAM1 has been investigated as a biomarker for coronary artery disease, and one study found that plasma NCAM1 levels were negatively correlated with coronary artery disease." (PMID 38500750, 2024).
dementia (5 papers, 2014 to 2025). Loss of intellectual abilities interfering with an individual's social and occupational functions. "A previous study of temporal lobe proteomes reported a significant upregulation of NCAM1 only in the brains of male dementia patients." (PMID 40877285, 2025). "Specifically, the NCAM1 and PZP proteins showed sex-specific causal relationships with dementia in males and females, respectively." (PMID 40877285, 2025). "From sex-stratified Mendelian randomization using the SD-pQTLs, proteins NCAM1 and PZP showed significant causal relationship with dementia in males and females, respectively." (PMID 40877285, 2025). "For male-specific relationships, SUSD4-inflammatory bowel disease (Inverse variance weighted (IVW) fixed effects meta-analysis MR estimate q-value in males = 0.038, in females = 1.00) and NCAM1-dementia (q-value in males = 0.045, q-value in females = 1.00) pairs were identified." (PMID 40877285, 2025). "Notably, the survival analyses of PZP and NCAM1 on dementia showed the same direction of effect as in the MR, suggesting the possibility of insufficient sample size." (PMID 40877285, 2025).
Hypertension (5 papers, 2017 to 2024). The presence of chronic increased pressure in the systemic arterial system. "Moreover, the effect of Tianma on correcting the function and activity of Tpi1, Ppia, Ncam1, Uchl1, Septin-2 and Hsp90aa1 proteins, provided conclusive evidence for Tianma in the treatment of seizures, hypertension and headaches." (PMID 29262557, 2017).
ischemic stroke (5 papers, 2016 to 2025). A stroke disorder caused by obstruction of blood flow to the brain, due to thrombotic (local blood clot formation) or embolic (due to a blood clot or other material traveling from another site) event. "NCAM1 as a member of the immunoglobulin superfamily is reported to be implicated in the expansion of T cells and dendritic cells which play a role in immune surveillance, and is identified as key genes associated with ischemic stroke." (PMID 28828208, 2017).
lupus nephritis (5 papers, 2015 to 2024). Glomerulonephritis in the context of systemic lupus erythematosus. "Similar to the association of EXT1 and EXT2 with lupus nephritis, NCAM-1 was reported as an antigen for membranous lupus nephritis (MLN) and PMN." (PMID 33808418, 2021). "The IgG1 dominance for anti-NCAM-1 antibodies shares similarity with anti-EXT1/EXT2 antibodies, supporting the association of both NCAM-1 and EXT1/EXT2 with lupus nephritis." (PMID 33808418, 2021).